CD68 (CD68 molecule)
Diseases named in the same sentence as CD68 in open-access papers (continued):
Sharing a sentence is not in itself a finding about the gene and the disease.
liver fibrosis (continued). "Our results showed significant upregulation of multiple lysosomal proteins in Lal−/− livers, including CTSS and CTSD, which are known to be important mediators in liver fibrosis and liver cancer progression, along with CD68, a well-established macrophage marker." (PMID 37595802, 2023). "Interestingly, sharply increased expression of macrophage marker CD68 was also found in liver fibrosis tissues." (PMID 37941043, 2023). "In the human liver, the expression levels of Fmnl1 and Myh9 in the MMD system (CCR2/CD68/CD11c+ cells in humans) were also increased with collagen deposition, and the expression levels of Fmnl1 and Myh9 increased with aggravation of the liver fibrosis stage (all p<0.05)." (PMID 36911682, 2023). "Administration of the antihypertensive agent hydralazine to SHRs significantly ameliorated HFC-induced liver fibrosis; it suppressed the aggregation of CD68-positive macrophages and the upregulation of platelet-derived growth factor receptor beta, and collagen, type 1, alpha-1 chain." (PMID 33315911, 2020). "In addition, we immunohistochemically stained NAFLD liver section for CD68, as CD68 positive cells significantly increased with the progression of liver fibrosis." (PMID 27739482, 2016). "Immunohistochemical staining of liver sections showed a marked increase of CD68 positive macrophages and neutrophils (positive for neutrophil elastase) in both CCl4- and BDL-induced liver fibrosis." (PMID 36514072, 2022). "To determine the changes in macrophage phenotype after treatment of exosomes, we use immunofluorescence to label CD68 and CD163 in paraffin sections of liver fibrosis." (PMID 36183106, 2022). "Western blot of liver lysates showed that inflammatory molecules, COX-2, MCP-1, CD68, and neutrophil elastase were strongly increased in CCl4- and BDL-induced liver fibrosis, compared to sham control mice." (PMID 36514072, 2022). "A previous study showed that infiltrated macrophages expressed CD68, CCR‐2, and Ly6c and that CCR‐2−/− mice had less inflammatory cell infiltration and hepatic fibrosis, suggesting that hepatic recruitment of macrophages promotes NASH through CCR‐2." (PMID 34390210, 2021). "M1 macrophages represent high expression of CD86, CD68, and iNOS, and secrete the pro-inflammatory factors such as TNF-α, IL-6, and ROS, that exacerbate the hepatic inflammation and tissue injury and promote the development of hepatic fibrosis." (PMID 41375167, 2025). "Furthermore, we found that co-expression of CD68 and a-SMA was found elevated in liver fibrosis tissues and hardly any in the normal liver tissues, which indicated that MMT cells were present in liver fibrosis." (PMID 37941043, 2023). "CD68 and CD206 markers predominantly gathered in liver fibrosis samples." (PMID 37941043, 2023). "Western blot revealed that CD68 was significantly decreased, whereas CD206 was contrarily increased in the mouse livers of the 3D-Exo group, indicating treatment with the 3D-Exo reversed the progression of the liver fibrosis." (PMID 34930304, 2021). "Matrine prevented MCD diet-induced inflammation and fibrosis in the liver after 6 weeks of treatment, as demonstrated by a matrine-induced suppression of the increases in TNFα, CD68, MCP-1 and NLRP3, and hepatic fibrosis proteins (TGFβ, Smad3, and collagen 1) induced by MCD diet." (PMID 31068812, 2019). "Therefore, we evaluated the expression of CD68 in our in vivo experiment, and PEA would attenuate liver fibrosis by inhibiting activation of HSCs as well as Kupffer cells." (PMID 30057547, 2018). "However, it increased the expression CD68 and proinflammatory cytokines in the presence of DMN-induced liver fibrosis." (PMID 22531084, 2012). "GdCl3 might inhibit ED2 macrophages, which are transformed into ED1 macrophages in the lungs in DMN-induced liver fibrosis, so the number of ED1 macrophages (CD68 expression) increased in the lungs." (PMID 23237422, 2012).
liver fibrosis (continued). "To investigate whether inflammation and intrahepatic thrombosis play a role in the development of liver fibrosis in rats with PAH, we next performed IHC for the coagulatory marker fibrin and the immune cell markers CD3 (T-cells), CD19 (B-cells) and CD68 (macrophages)." (PMID 35369312, 2022). "At the chosen time-point (week 17), we observed a clear liver fibrosis in both DEN doses in male mice (DEN10/CCl4 and DEN50/CCl4), characterized by increased collagen accumulation (Sirius red), HSCs activation (α-SMA), increased population of CD68+ macrophages and activation of COX-2/IL-6 axis." (PMID 30212575, 2018). "Therefore the levels of liver fibrosis and inflammation might be correlated with CD80 expression on CD68+ cells because both phenomena are influenced by PGE2." (PMID 27348308, 2016). "These may be related to the GdCl3-induced increase in CD68 and proinflammatory cytokines, which leads to no significant inhibitory effects in the serum, and no marked improvement in liver fibrosis." (PMID 23237422, 2012). "We did not observe any ectopic infiltration of monocytes/macrophages one week after the BH treatment in the left lateral lobe (LLL) of the liver, compared with the basal CD68 expression level in non-fibrotic healthy liver tissue and in BH-untreated lobes with TAA-induced liver fibrosis." (PMID 38956264, 2024).
colitis (37 papers, 2012 to 2026). Inflammation of the colon. "We found that colitis caused a reduction of Iba-1 and CD68 immunoreactivity, microglial activation markers, in specific brain regions of the limbic system such as the medial prefrontal cortex (mPFC), while other areas remained unaffected." (PMID 31882991, 2019). "Immunofluorescence staining of colon tissue revealed that DSS-induced colitis resulted in a pronounced upregulation of pro-inflammatory macrophage markers, specifically CD68 and CD86, which are associated with M1 macrophage polarization and heightened inflammatory responses." (PMID 40725052, 2025). "Small NBO2 water significantly reduced disease activity index scores, histopathological colitis scores, colonic shortening, CD68-positive inflammatory macrophage density, and tumor numbers." (PMID 41752110, 2026). "Immunofluorescence examination of sigmoid colonic tissues demonstrated that DSS-induced colitis significantly upregulated pro-inflammatory macrophage markers (CD68, CD86) while downregulating the anti-inflammatory marker CD163 relative to NC." (PMID 40725052, 2025). "Meanwhile, rhMANF treatment significantly reduced macrophage infiltration in colitis mice, as shown by CD68 staining." (PMID 36635421, 2023). "The expressions of RFZ1, IL-6, TNF-α, and IL-1β were also increased in CD68+ macrophage detected by IF staining in the colon from mice with colitis." (PMID 37733446, 2023). "In the colitis model cohort, a hefty number of CD-68+ macrophages were detected in both the sub-epithelial and lamina propria regions." (PMID 37328528, 2023). "To further confirm this result, we also double-labeled MANF and CD68 in colon tissues of mice with colitis." (PMID 36635421, 2023). "More importantly, FCNB was specifically colocalized with CD68+ macrophages recruited into the colon of mice with colitis." (PMID 36932401, 2023). "Increased immunopositivity of TNF-α, vascular endothelial growth factor (VEGF) and CD68 markers was observed in the colitis group cells, and decreased level of this positivity was observed in MSCs treated group." (PMID 36228298, 2022). "IMC computational analysis of the liver from mice with transfer colitis suggested that VSOPs were taken up mainly by the Kupffer cells in the liver (F4/80+, CD68+ and Ly6G−)." (PMID 35903065, 2022). "In transfer colitis mice, VSOPs co-localize to F4/80, CD68 double positive macrophages to a much lesser extent." (PMID 35903065, 2022). "Semi-quantitative analysis showed that the proportion of CD68-positive cells in the colon of colitis mice was significantly increased (P < 0.05)." (PMID 35346043, 2022). "The results of established colitis treatment showed that the neutralization of TNF-α by the antibody generated a reduction in CD68 and myeloperoxidase (MPO) markers, indicating a reduction in macrophages and neutrophils in the colon tissue." (PMID 35939430, 2022). "Tiliroside (25.0 and 50.0 mg/kg) treatments significantly decreased the percentage of M1 macrophage phenotype (CD68+ iNOS+ double labeled) and upregulated M2 macrophage phenotype (CD68+ CD206+ double labeled) in the colonic lamina propria of colitis mice." (PMID 33868286, 2021). "The IHC analysis demonstrated that CD11b/CD68 positive cells were significantly higher in active colitis and dysplasia than in inactive colitis." (PMID 33995655, 2021). "Iba-1 mRNA levels were decreased and CD68 expression was unaltered in mice with DSS colitis, confirming the immunohistochemical findings at the transcriptional level in this brain area." (PMID 31882991, 2019). "Increased infiltration of CD68-positive macrophages was detected in the inflamed mucosa of the colitis-induced mice." (PMID 28842625, 2017). "Sodium propionate inhibited macrophages with CD68 marker infiltration into the colonic mucosa of colitis mice." (PMID 27574508, 2016).
colitis (continued). "In colitis-associated tumorigenesis, in contrast to WT mice, all CD68–mEPRAP transgenic mice survived the AOM/DSS treatment, and CD68–mEPRAP transgenic mice developed fewer polyps." (PMID 26439841, 2015). "Moreover, these molecules have been demonstrated to inhibit the infiltration of TCD3+ cells and CD68+ macrophages in the intestinal mucosa, thereby alleviating colitis by reducing the production of pro-inflammatory cytokines TNF-α and IL6 by macrophages." (PMID 40130239, 2025). "However, in DSS-induced colitis VSOPs further strongly co-localized with CD68, F4/80 double positive macrophages expressing CD44." (PMID 35903065, 2022). "CD68 immunoreactivity was also altered by colitis in a brain region-specific manner." (PMID 31882991, 2019). "In addition, we measured immunoreactivity of the microglial activation marker CD68 in these areas and detected similar colitis-induced reductions in MeA and CA1, suggesting reduced microglial activation during colitis." (PMID 31882991, 2019). "However, sodium propionate reduced the expression of CD68 in the colon compared with DSS-induced colitis mice." (PMID 27574508, 2016). "The number of CD68+ cells, a pan macrophage marker, was increased in biopsies from patients with active disease, those in medically induced remission, as well as those with a prior history of colitis." (PMID 22723974, 2012). "Thus, we explored the CD68 expression in DSS-induced colitis model mice." (PMID 38467701, 2024). "Flow cytometry was performed on brain single cell suspensions to further characterize activated microglia during acute colitis using several markers, including CD45, CD11b, P2RY12, CD11c, CD68, CX3CR1, and LAMP1." (PMID 40457749, 2025). "This is emphasized by a significant lower abundance (p = 0.001592) of total amount of VSOPs containing F4/80+, CD68+ macrophages, expressing CD44 in transfer colitis." (PMID 35903065, 2022). "In the model of mice colitis, we also found that p-STAT3 and AChE increased expressed in intestinal CD68-positive cells in DSS mice compared with sham ones." (PMID 27977009, 2016). "At 2 weeks after the second course of DSS colitis, we examined colonic mucosa for inflammation by staining colonic sections for MPO, Gr1 (neutrophil marker) or CD68 (macrophage marker) by immunofluorescence staining method." (PMID 26951793, 2016). "To address this issue, we examined immune cell populations in colitis-sensitive and colitis-resistant mouse models by immunohistochemistry (IHC) staining of myeloperoxidase (MPO; for neutrophils), CD68 (for macrophages/monocytes), CD4, and CD8 on colon sections from different mouse strains." (PMID 40749055, 2025). "In line with the immunohistochemical data, DSS-induced colitis significantly reduced Iba-1 gene expression (t6.3 = 5.5; p = 0.001), but did not change CD68 expression within this brain area." (PMID 31882991, 2019). "In response to PNU-282987 treatment, we detected a significantly decreased number of CD68+M1 macrophages compared with the colitis model group, while the number of CD68+CD163+ M2 macrophages did not change, and the overall ratio of M1/M2 macrophages decreased significantly." (PMID 36058917, 2022). "Interestingly, however, the effects of colitis on Iba-1 and CD68 immunoreactivity are not identical." (PMID 31882991, 2019). "However, the current data show that WAS does not affect brain Iba-1 or CD68 levels both during colitis or control conditions." (PMID 31882991, 2019). "Moreover, not every brain area examined appears to be affected to the same extent, given that neither the Iba-1 nor the CD68 profile of some brain areas (CA3, LH) changed during colitis." (PMID 31882991, 2019). "In contrast, hypothalamic CD68 expression in the PVH and LH was not affected by colitis." (PMID 31882991, 2019).
hepatocellular carcinoma (35 papers, 2012 to 2025). A malignant tumor that arises from hepatocytes. "Previous research has shown that elevated levels of KRTCAP2 protein are associated with reduced infiltration of CD8+ T cells and CD68+ macrophages in hepatocellular carcinoma tissues." (PMID 40315225, 2025). "While CD68+ macrophages are associated with poor prognosis, a significant decrease in CD68+ macrophage infiltration has been found in hepatocellular carcinoma peritumoral TLS." (PMID 37529035, 2023). "CD248 expression in cancer-associated fibroblasts promotes hepatocellular carcinoma progression through interaction with CD68 on macrophages and consequent polarization to the tumor-promoting M2 phenotype." (PMID 36401329, 2022). "Over expression of CD68 along with other tumor associated macrophages is associated with worse prognosis in hepatocellular carcinoma patients." (PMID 33415077, 2020). "Our previous study has found that the abundance of peritumoral CD68+ macrophages was associated with poor prognosis in hepatocellular carcinoma (HCC) after resection." (PMID 23555776, 2013). "In liver carcinomas, CD68 is typically used to denote the macrophages that have infiltrated the tumor." (PMID 38967628, 2024). "In hepatocellular carcinoma, an increase in M1 macrophages associated with increased time until recurrence, and a reduced CD163/CD68 ratio was correlated with a worse outcome, which corroborates, at least partially, our results." (PMID 31481956, 2019). "It is reported that CD68+HLA-DR+ TAMs in hepatocellular carcinoma (HCC) can promote migration of HCC cells via the NF-κB/FAK pathway." (PMID 27975071, 2016). "Histological analyses revealed that in human hepatocellular carcinoma (HCC) specimens, the expression levels of ER stress markers such as BiP, ATF6, PERK, and IRE1α were closely associated with an elevated infiltration of CD68+PDL1+ macrophages." (PMID 38106991, 2023). "Similar to findings of M2-like CD163+ TAMs, the presence of CD68+ TAMs is associated with poor prognosis in nasopharyngeal carcinoma (NPC), gastric and hepatocellular cancers, this study investigated whether CD68+ TAMs could also be adopted as a prognostic indicator in OSCC." (PMID 37397243, 2023). "For example, CD68+HLA-DR+ TAMs in hepatocellular carcinoma (HCC) induce HCC cell migration via the nuclear factor kappa B (NF-κB)/ focal adhesion kinase pathway." (PMID 33613850, 2021). "In a separate hepatocellular carcinoma cohort, we replaced the stromal component with specific immune cell types—CXCR3+CD68+ or CD8+—to profile their spatial relationships with CXCL9+CD68+ cells." (PMID 39965007, 2025). "Our findings demonstrated a statistically significant elevation in CD68 and CD206 expression in the sublethal heat treatment group compared to the standard hepatocellular carcinoma group." (PMID 38274825, 2023). "To better characterise PD-L1 expression in hepatocellular carcinoma (HCC), we analysed its expression patterns in 453 HCC patients by double staining for CD68 and PD-L1 using the Tyramide Signal Amplification Systems combined with immunohistochemistry." (PMID 29921949, 2018). "In this study, we also found celecoxib administration can reduce FOXP3+ Tregs, CD68+ TAMs, and PD‐L1 expression and increase CD8+ CTLs in hepatoma tissues during epirubicin therapy." (PMID 29683262, 2018). "In order to investigate immune cells densities in hepatocellular carcinoma, immunohistochemistry was performed using antibodies including α-MPO(neutrophils), α-CD-68(macrophages), α-CD-3(T-cells), α-CD-20(B-cells), α-CD-4(CD4+ T-cells) and α-CD-8(CD8+ T-cells)." (PMID 34104178, 2021). "CK7 and CD68 immunostains should be used together, as a small proportion of typical hepatocellular carcinomas can be CD68 positive, and a significant minority of typical hepatocellular carcinomas can also be CK7 positive, in particular hepatocellular carcinomas in children and young adults." (PMID 24278737, 2012).
hepatocellular carcinoma (continued). "In HBV-infected distal non-tumor liver tissues from hepatocellular carcinoma patients, colocalization of the PGLYRP2/HBV capsid complex with CD68, a pan-macrophage marker, was demonstrated using multiplex immunofluorescence staining, suggesting the presence of the complex within liver macrophages." (PMID 39946201, 2025).